SNORD36C (small nucleolar RNA, C/D box 36C)
Synonyms: U36c; RNU36C
Gene: Small nucleolar RNA gene on chromosome 9 (133,350,847 to 133,350,912, forward strand). Ensembl gene ENSG00000252542.
Gene Ontology:
Biological process: RNA processing
Cellular component: nucleolus
Homologues: Orthologues: chimpanzee SNORD36 (100% identical), macaque SNORD36 (88% identical), guinea pig SNORD36C (80% identical), pig SNORD36 (79% identical), rat LOC120101984 (77% identical), dog SNORD36C (76% identical), zebrafish SNORD36 (71% identical), tropical clawed frog SNORD36 (70% identical). Paralogues in human: SNORD36A (62% identical), SNORD36B (58% identical), SNORD36 (48% identical).